TLR2 (toll like receptor 2)
Diseases named in the same sentence as TLR2 in open-access papers (continued):
Sharing a sentence is not in itself a finding about the gene and the disease.
HCMV infection (continued). "Furthermore, TLR2 plays an important role in controlling CMV infection both in humans and in mice." (PMID 25955717, 2015). "HCMV infection may upregulate the expression of TLR2 and TNF-α." (PMID 25435993, 2015). "TLR2, TRL3, and TLR9 were determined as inducing the expressions of IFN-β and tumor necrosis factor alpha (TNF-α) at early times during HCMV infection in human THP-1 cells, as well as in human foreskin fibroblasts (HFF)." (PMID 30241345, 2018). "Other studies also showed the SNPs located in TLR2, as well as in TLR3, TLR4, TLR7 and TLR9 genes, to be contributing to HCMV infection." (PMID 28118851, 2017). "Numerous in vitro studies confirmed the role of TLRs in immunity to CMV infection and it was proven that TLR4 and TLR2 recognize CMV." (PMID 27586547, 2016). "In this study we demonstrate that in addition to MICB and the secretome pathway, HCMV miR-UL112-3p modulates the TLR/IRAK1/NFκB signaling pathway by targeting TLR2, a HCMV sensor that plays an important role in mammalian control of CMV infection." (PMID 25955717, 2015). "In the present study, the mRNA of TLR2 and its downstream inflammatory factor, TNF-α, were upregulated with the increased expression of IE1–72 in SW480 cells following HCMV infection." (PMID 25435993, 2015). "Herein, we show that in the non-sex-stratified analysis, HCMV infection had little impact on in vitro innate cytokine responses to a panel consisting of TLR2, 4, 5 and 7/8 ligands, except for reduced TNF-α reactivity to TLR2 stimulation with HKLM." (PMID 32707906, 2020). "HCMV infection stimulates cluster differentiation antigen 14 (CD14), TLR2, TLR4, and TLR5 on the surface to enhance the intracellular expression of the adaptor protein MyD88, and phosphorylation of IκB and NF-κB, thereby increasing the response of macrophages to viral components." (PMID 33298111, 2020). "Therefore, the current paper was aimed to describe the role of TLR2, TLR4 and TLR9 SNPs in the occurrence of HCMV infection among pregnant women, acquired within the gestation period." (PMID 28340580, 2017). "The results showed that TLR2 SNPs rs121917874, rs5743708, and TLR4 SNP rs4986790 are not related to risk of HCMV infection in infants." (PMID 28046022, 2017). "Among pregnant women, the low genotypic variability within TLR2 and TLR4 SNPs seems to be the important cause of the lack of any associations with HCMV infection." (PMID 28340580, 2017). "However, other studies showed some role of SNPs in TLR2, TLR3, TLR4, TLR7 and TLR9 genes in HCMV infections." (PMID 25844529, 2015). "In the absence of such experiments, we cannot formally rule out that miRNA-mediated manipulation of TLR2 has non-NFκB effects, or even no consequential effect, relevant to HCMV infection." (PMID 25955717, 2015). "PECs from TLR4−/− mice showed normal IL-6 production in response to CMV infection, while PECs from TLR2−/− secreted no detectable IL-6." (PMID 23061052, 2012). "Therefore, our results suggest that HCMV infection suppresses innate reactivity to TLR2 and TLR7/8 stimulation in infant females but not in males." (PMID 32707906, 2020). "However, TLR2/6 heterodimers do not co-precipitate in human cytomegalovirus (HCMV) infection." (PMID 36171749, 2022). "In addition to NFκB, TLR2 signals through other pathways including P38, JNK and Interferon Response Factors (IRFs) that could potentially play a major role in the TLR2-dependent modulation of HCMV infection." (PMID 25955717, 2015). "So far, no other study has shown before any possible involvement of TLR2 2258 G > A, TLR4 896 A > G and TLR4 1196 C > T SNPs in the occurrence of HCMV infection during pregnancy." (PMID 28340580, 2017). "TLR2 biphasic expression was not a loading artifact since probing the same blot for TRAM1, a protein that remains constant during HCMV infection, indicated fairly consistent loading between the lanes." (PMID 25955717, 2015).
HCMV infection (continued). "Similarly to our study, almost the same frequencies of distinct genotypes in both TLR2 2258 G > A and TLR4 896 G > A SNPs were determined in patients with transplants, with and without clinical signs of HCMV infection." (PMID 28340580, 2017). "Thus, pre-treatment of HFF with TLR3 and TLR4 ligands, but not TLR2 or TLR9 ligands, inhibited HCMV infection." (PMID 18053251, 2007).
meningitis (23 papers, 2007 to 2025). A disorder characterized by acute inflammation of the meninges of the brain and/or spinal cord. "Subsequent comparative analyses in an experimental meningitis model, however, implicated the concerted action of TLR2 and TLR4, while negating a role for TLR9 in the innate immunological perception of pneumococcal CNS infection." (PMID 38358825, 2024). "Although TLR2 has been suggested to be implicated in S. suis meningitis, further in vivo studies with TLR2−/− mice are warranted." (PMID 23724118, 2013). "Combined carriership of TLR2+2477 GG (WT) and TLR4+896AG (mutants) increased the risk to develop post-meningitis hearing loss, indicating that TLR2 SNPs compensate for TLR4 mutant hyporesponsiveness." (PMID 22662111, 2012). "Our treatment study compares the host response mediated by TLR2 and CD14 in meningitis, and illustrates the requirement and success of adjuvant therapy, under conditions of harmful inflammation in TLR2-deficient mice." (PMID 17428319, 2007). "In fact, the actual in vivo role of TLR2 in meningitis caused by any strain of S. suis is unknown, and it would be difficult to predict." (PMID 23724118, 2013). "TLR4+896 mutants are highly associated with post-meningitis hearing loss and combined carriership of the TLR2+2477 WT with TLR4+896 mutant alleles as well as the combination of TLR4+896 mutant alleles with TLR9 -1237 mutant alleles significantly increases this risk." (PMID 22662111, 2012). "We next examined whether clinical disease phenotype, pulmonary or meningeal disease, influenced the association between TLR2 T597C and bacterial genotype." (PMID 18369480, 2008). "This fundamental difference in TLR2 and TLR4 functions during E. coli meningitis provides new insights into how pathogens can differentially engage host receptors, with TLR2 being co-opted for invasion while TLR4 primarily mediates inflammatory damage." (PMID 40821830, 2025). "This choice was influenced by the observation that Tlr2/4–/– mice exhibited reduced inflammation and brain pathology in the early stages of meningitis before antibiotic treatment." (PMID 38358825, 2024). "Strikingly, the meningitis phenotype of Tlr2–/– Tlr4–/– (Tlr2/4–/–) double-knockout (double-KO) mice was stronger than that of Tlr2–/– mice, yet significantly milder than that of Myd88–/– mice." (PMID 38358825, 2024). "Consistent with the requirement of TLR2 interaction with Ecgp96 TLR2−/− newborn mice are resistant to infection while TLR4−/− animals are very vulnerable to the development of meningitis." (PMID 26744349, 2016). "TLR2 KO mice demonstrated an increased disease severity together with a moderately enhanced bacterial growth in the central nervous system during meningitis induced by intracisternal injection of pneumococci." (PMID 17711480, 2008). "TLR2 activation was involved in the pathogenesis of meningitis induced by S. suis strains." (PMID 37111486, 2023). "However, a previous study on mouse meningitis induced by E. coli showed that TLRs were activated in brain tissues, with elevated Tlr2, Tlr4 and Tlr7 expression." (PMID 32509459, 2020). "A study on meningitis model showed increased bacterial level and enhanced disease in TLR2-/- mice." (PMID 26214513, 2015). "However, other studies showed that TLR2−/− mice are significantly more affected and have increased bacterial loads than WT mice in experimental meningitis." (PMID 23724118, 2013). "It is still to be determined whether TLR2 expression upon E. coli K1 infection has any role in the pathogenesis of meningitis." (PMID 21124939, 2010). "Consequently, expanding treatment with TLR2 and -8 blockade to meningitis patients at the initiation of antibiotic therapy — ideally as quickly as possible upon suspected diagnosis — may be a promising therapeutic approach." (PMID 38358825, 2024).
meningitis (continued). "There was an overall association of TLR2 T597C with meningeal disease (OR = 1.51 [95% C.I. 1.12–2.03] P = 0.006) but this was not significant for meningeal disease caused by non-Beijing isolates (control vs. TBM non-Beijing OR = 1.25, [95% C.I. 0.86–1.82], P = 0.243)." (PMID 18369480, 2008). "By subjecting specific TLR-KO mice to experimental pneumococcal meningitis, we demonstrated the concerted activity of cell-surface TLR2 and endosomal TLR13 as drivers of brain pathology in meningitis." (PMID 38358825, 2024). "Three types of Toll-like receptors (TLR2, TLR4, TLR9) have been identified as the ones that are involved in S. pneumoniae meningitis." (PMID 39121090, 2024). "Because both strains showed excessive TNF, we compared the treatment response in wt, TLR2-/-, CD14-/-, and CD14-/-/TLR2-/-double knockout mice with meningitis to antibiotic treatment and/or anti-inflammatory treatment with TACE inhibitor." (PMID 17428319, 2007). "From our in vivo studies using single knockout mice, it appears that TLR2 and CD14 both are protective in meningitis, although by different mechanisms." (PMID 17428319, 2007). "Consistently, in our study, Tlr2/4–/– and Tlr2/3/4/7/9–/– mice displayed comparable phenotypes, while the phenotype of Tlr3/7/9–/– mice was largely indistinguishable from that of WT mice, arguing against a key role of TLR3, -7, and -9 in pneumococci sensing and thus meningitis pathology." (PMID 38358825, 2024). "The more pronounced disease phenotype in Tlr2/13–/– mice compared with Tlr2/4–/– mice prompted us to introduce the endosome inhibitor CQ as a TLR13 blocker, combined with the mouse-human cross-reactive neutralizing TLR2 monoclonal antibody T2.5 in our murine meningitis model." (PMID 38358825, 2024). "However, an attenuated increase in CSF IL-1β concentration in TLR2/4 GKO mice in our meningitis mouse model did not confer protection from learning impairment in mice subjected to patrolling or reversal tasks." (PMID 31700009, 2019).
periodontal disease (23 papers, 2013 to 2026). "Toll-like receptor 2 (TLR2) activation has been implicated in the pathogenesis of periodontal disease but the identity of the TLR2 agonists has been an evolving story." (PMID 35048038, 2021). "Collectively, this study linked dentilisin with TLR2 activation and identified potential tissue specific inducible MMPs that may play additional roles in mediating host inflammatory responses in periodontal disease." (PMID 34950607, 2021). "ROC curve analysis indicated that TLR4 had higher specificity and sensitivity than TLR2 in diagnosing periodontal disease." (PMID 40371381, 2025). "Am enhances immune defense against Pg-induced periodontal disease by modulating the TLR2-C5aR-MyD88 signaling pathway." (PMID 40299200, 2025). "A number of candidate gene studies showed that IL1A, IL1B, IL4, IL6, IL10, TNFA, FcγR, VDR, TLR2, TLR4, and MMP1 were the main genes associated with periodontal disease." (PMID 36294882, 2022). "In the present study, we observed a significant increase in TLR-2 gene expression in all groups of animals submitted to experimental periodontal disease." (PMID 34884653, 2021). "P. gingivalis also directs important inflammatory perturbances observed in periodontal disease, such as modulating cross talk between toll-like receptor (TLR)-2 and C5aR." (PMID 34950607, 2021). "Although both TLR2 and TLR4 have been implicated in periodontal disease progression, various studies utilizing knockout mice and in vitro systems suggest that TLR2 plays the most direct role is in sensing various components produced by periodontal pathogens that drive alveolar bone destruction." (PMID 34255809, 2021). "In conclusion, the findings presented in this paper demonstrated the cell-mediated anti-inflammatory activity of SAGE in the treatment of chronic inflammatory diseases such as periodontal disease, is mediated at least in part through TLR-2 and TLR-4 signaling pathway." (PMID 34481488, 2021). "Periodontal disease caused by gram-negative bacteria stimulates the production of inflammatory cytokines (via Toll-like receptor 2 and 4), promoting a progressive destruction of periodontal tissue." (PMID 28906456, 2017). "Toll-like receptors (TLR2 and TLR4) are crucial in the detection of pathogen-associated molecular patterns (PAMPs) during periodontitis, resulting in exacerbated production of proinflammatory cytokines and ultimately tissue damage and bone loss associated with this periodontal disease." (PMID 40371381, 2025). "However, numerous recent reports suggest that MyD88-independent TLR2 pathways may also contribute to periodontal disease progression." (PMID 34255809, 2021). "In addition to TLR2 and TLR4, other TLR associations to periodontal disease have been investigated." (PMID 29621153, 2018). "For practical reasons, we arbitrarily selected only two gram-negative microorganisms associated with periodontal disease: due to their distinct potencies in activating TLR2/TLR4 and also because of the distinct virulence factors expressed by these bacteria (e.g., leucotoxin)." (PMID 28114408, 2017). "Toll-like receptors (TLR-2 and TLR-4) and tumor necrosis factor-alpha (TNF-α) are key mediators of immune signaling and tissue breakdown, making them potential biomarkers of periodontal disease activity." (PMID 42154854, 2026). "In order to make the most meaningful comparison of a TLR2 to a TLR4 agonist, we chose to test standard E. coli K12 LPS against LPS from P. gingivalis (the etiological agent of periodontal disease)." (PMID 23382974, 2013). "Our study provides original evidence that the putative oral pathogen F. alocis is capable of inducing COX2 at transcriptional and protein levels in human fibroblastic and monocytic cells through TLR2 and MAPK signaling, suggesting a role of F. alocis in the etiopathogenesis of periodontal diseases." (PMID 32089643, 2020). "Both TLR2 and TLR4 are largely involved in progression of periodontal disease." (PMID 29582430, 2018).
periodontal disease (continued). "Contrasting these studies, in a cohort of Turkish individuals it was reported that neither TLR2, nor TLR4 polymorphisms were able to distinguish periodontal disease." (PMID 29621153, 2018). "This prospective, non-randomized interventional study evaluated TLR-2, TLR-4, and TNF-α levels in gingival crevicular fluid (GCF) for periodontal disease monitoring and assessed the effects of nonsurgical periodontal therapy (NSPT) on clinical parameters." (PMID 42154854, 2026).
Cognitive impairment (22 papers, 2011 to 2026). Abnormal cognition is characterized by deficits in thinking, reasoning, or remembering. "Among these, TLR2 expression is thought to be strongly associated with cognitive impairment with either prenatal or postnatal stimuli." (PMID 37627253, 2023). "TLR2/4−/− mice are protected from cognitive impairment following Aβ immunisation with polymorphism in the tlr2 and tlr4 gene linked with AD." (PMID 23671673, 2013). "The presence of TLR2 is believed to be essential for regular cognitive function, as knocking out TLR2 (TLR2−/−) in mice caused enlargement of ventricles, and behavioural and cognitive impairment." (PMID 37627253, 2023). "Aif1 and Tlr2 were the only genes significantly associated with spatial recognition memory, implying that bacterial lipoprotein content and microglial proliferation may be involved in diet-induced cognitive impairment." (PMID 32066702, 2020). "As our results showed that WS rats have cognitive impairment and ventricle enlargement, our aim was to evaluate Tlr2 levels in the hippocampus." (PMID 33500541, 2021). "Psychotic symptoms such as hyperlocomotion, anxiolytic-like behaviors, prepulse inhibition deficits, social withdrawal, and cognitive impairments were observed in TLR-2 knock-out (KO) mice." (PMID 25687169, 2015). "However, the contribution of TLR2 and TLR4 ligands in brain tissue to the aging-associated cognitive impairments and molecular mechanisms involved remains to be determined." (PMID 37681885, 2023). "Furthermore, in such mice, providing training repeatedly improved their learning ability and memory, suggesting molecular pathways other than TLR2 are involved in cognitive deficits." (PMID 37627253, 2023). "In the present study, in old mice with naturally evolved cognitive impairments, concentrations of TLR2 and TLR4 ligands, e.g., lipoteichoic acid and bacterial endotoxin were also higher in both brain regions studied when compared to young animals without cognitive impairments." (PMID 37681885, 2023). "Comparably in humans, antipsychotic drugs increased TLR2 (MFI) expression in monocytes of patients with schizophrenia, indicating a possible association between TLR2 and cognitive performance by which antipsychotic medication ameliorates cognitive impairment." (PMID 37627253, 2023). "TLR2 was found to play a pivotal role in inflammation after ischemic brain injury and was involved in the development of diabetic microvascular complications, including endothelial dysfunction and cognitive impairment." (PMID 35221911, 2022). "Although TLR2 is shown to play a role in cognition, it would be incorrect to assume that it is the only pathway that might be involved in cognitive deficits in schizophrenia; other pathways or other TLRs such as TLR3 and TLR4 are involved with cognitive performance as well." (PMID 37627253, 2023). "Elevated TLR signaling through TLR2, TLR4, and TLR9 correlates with frailty, cognitive impairment, and functional decline." (PMID 41373468, 2025). "Behavioral, molecular, and electrophysiological evidence indicates that early minor stimulation of microglial TLR2 and TLR4 receptors attenuates AD-related cognitive deficits in rats." (PMID 31509519, 2019). "Remarkably, in a POCD model, surgery induced neuroinflammation and cognitive impairment in C57BL/6J mice but not in TLR2−/− mice or those treated with a TLR1/TLR2 antagonist." (PMID 40558558, 2025). "In summary, long-term cognitive impairment of mice in the visual discrimination task was aggravated in the absence of TLR2/4 signalling during acute pneumococcal meningitis." (PMID 31700009, 2019). "Given that PPI deficits and impaired broad learning and memory system were presented in TLR-2 KO mice, impaired hippocampal neurogenesis in TLR-2 KO mice may contribute to sensorimotor gating dysfunction, resulting in PPI deficits and cognitive impairment." (PMID 25687169, 2015).
Cognitive impairment (continued). "However, how levels of TLR2 and TLR4 ligands and their signaling pathways are altered in the brain in the natural course of aging and if this is related to the development of cognitive impairments and changes of intestinal microbiota and barrier function has not yet been assessed." (PMID 37681885, 2023).